IGF1 (insulin like growth factor 1)
Diseases named in the same sentence as IGF1 in open-access papers (continued):
Sharing a sentence is not in itself a finding about the gene and the disease.
hypogonadism (continued). "Patients with high levels of GH, GH nadir, and IGF-1 were more likely to develop hypogonadism, with GH/IGF-1 inhibition on the hypothalamic-pituitary-gonadal axis being a possible etiology." (PMID 35154007, 2021). "In accordance with their low fat mass, SBA mice exhibited hypogonadism, alterations of key endocrine parameters (hypoleptinemia, modifications in the GH/IGF-1 axis)." (PMID 25090643, 2014). "Interestingly, we did see some variation in the changes in TT and IGF-1 across the various etiologies of hypogonadism." (PMID 40421427, 2025). "However, literature on the potential actions of clomiphene to alter IGF-1 levels in normal males treated for hypogonadism is quite sparse." (PMID 40421427, 2025). "We sought to examine the effects of clomiphene therapy on IGF-1 levels in nonacromegalic male patients treated with clomiphene for underlying hypogonadism." (PMID 40421427, 2025). "IGF-1 levels negatively correlated with biochemical hypogonadism (ρ = − 0.585; p = 0.028)." (PMID 37306894, 2024). "Men and women with hypogonadism had significantly lower IGF-1 levels than eugonadal patients." (PMID 37775530, 2023). "However, in our second case, pretreatment hypogonadism and a low IGF-1 concentration both recovered after chemoradiotherapy." (PMID 37697216, 2023). "Especially, case 3 was overweight, showed hypogonadism, and had high fasting insulin which could be attributed to the patient’s elevated levels of serum GH, IGF-1, and PRL." (PMID 35002961, 2021). "Other causes of the wasting are an inadequate calorie intake, reinforced by a diminished appetite due to uremia, multiple comorbid hormonal disorders (insulin and insulin IGF-1 resistance, hypogonadism, hyperparathyroidism) and metabolic acidosis, inhibiting protein synthesis." (PMID 32795277, 2020). "In their manuscript, Reid and colleagues found that both male sex and IGF-1 xULN were positively and significantly associated with the estimated skeletal muscle mass in their cohort, while nor age neither the presence of hypogonadism had a significant impact on it." (PMID 38967765, 2024). "All these findings suggest that the changes in phosphorus levels may be more associated with increased GH and IGF-1 rather than hypogonadism." (PMID 35340319, 2022). "Given the decrease in IGF-1 can be ≥2 SD in some patients and thereby potentially clinically significant, we recommend interval monitoring of serum IGF-1 in patients with hypogonadism treated with clomiphene citrate." (PMID 40421427, 2025). "Differences in handgrip strength between the two groups (hypogonadism vs. no hypogonadism) remained significant after adjustment for age and BMI, but lost significance after adjusting for IGF‐1 (GFR did not significantly influence model 4)." (PMID 37674061, 2024). "In the present study, phosphorus levels were similar in patients with and without hypogonadism, and also GH and IGF-1 levels were also similar between these two groups." (PMID 35340319, 2022). "The remission rate and postoperative hormone status, including nadir GH and IGF-1 levels and hypogonadism, were not different among the three groups in our study." (PMID 35355553, 2022). "Although IGF-1<-2SD and hypogonadism did not retain significance in the height-adjusted model, their high-risk associations in the uncorrected model suggest that growth hormone axis dysfunction and gonadal hormone deficiency remain potential underlying drivers of bone loss in TDT patients." (PMID 40671911, 2025). "Growth hormone (GH) and insulin-like growth factor 1 (IGF-1) levels, as well as concomitant hypogonadism, play an active role in calcium and CTX levels, while phosphorus levels are associated only with IGF-1 and GH rather than hypogonadism." (PMID 35340319, 2022). "Notably, although males with hypogonadism were not excluded from the study, adjustments were made for testosterone levels during analysis to enhance the accuracy of our assessment of the relationship between IGF-1 and BMD." (PMID 39398331, 2024).
hypogonadism (continued). "Furthermore, specifically designed trials are needed to dissect the consequences of altered sex steroid levels (e.g., in hypogonadism) from those arising from increased (or decreased) FSH levels on similarly affected target organs, and to better clarify the impact on, for example, the GH/IGF-1 axis." (PMID 37375761, 2023). "Patients with preoperative hypogonadism presented higher median baseline values of GH and IGF-1 (GH: 3.37 ng/mL; IGF-1: 551 ng/mL) compared to those without hypogonadism (GH: 1.36 ng/mL; IGF-1: 355 ng/mL)." (PMID 39337013, 2024). "Differences in hemoglobin levels between the two groups (hypogonadism vs. no hypogonadism) remained significant after adjustment for age, BMI, GFR and IGF‐1." (PMID 37674061, 2024).
pituitary tumor (57 papers, 2008 to 2026). A benign or malignant neoplasm affecting the pituitary gland. "On the contrary, higher IGF-1 xULN values at diagnosis [OR 2.304 (95%CI 1.254-4.234)] and a T2-weighted hypointense signal of the pituitary tumor [OR 18 (95%CI 1.754-184.679] were associated with a significantly higher likelihood of achieving a >50% IGF-1 reduction after SRL therapy." (PMID 34025586, 2021). "We report the case of a 34-year-old woman with a growth hormone (GH)/insulin-like growth factor 1 (IGF-1)-secreting pituitary tumor and multiple prior skull-base surgeries who presented with sudden-onset frontal headache." (PMID 41573480, 2025). "Paraclinical data included random growth hormone (GH) and insulin-like growth factor-I (IGF1) levels, maximal pituitary tumor diameter at diagnosis, first visit, and last evaluation." (PMID 38449845, 2024). "Subsequent outpatient monitoring revealed increased GH and IGF-1 levels, prompting a second surgery due to suspected pituitary tumor recurrence." (PMID 39331882, 2024). "Imaging found a 19 × 12 × 8 mm pituitary tumor, but her serum IGF-1 was within the reference, and nadir GH was 0.7ng/ml after glucose load at diagnosis." (PMID 39044175, 2024). "It is caused by a chronic excess of growth hormone (GH) and insulin-like growth factor 1 (IGF-1), in most cases as a result of a sporadic GH-secreting pituitary tumor." (PMID 39685770, 2024). "It is characterized by excessive secretion of growth hormone (GH) and insulin-like growth factor-1 (IGF-1), which is caused by a GH-secreting pituitary tumor in most cases and pituitary hyperplasia or ectopic GH or GH-releasing hormone secretion in rare cases." (PMID 37244996, 2023). "Symptoms arise due to a combination of both local effects, produced by a mass effect of the pituitary tumor, and systematic effects due to chronic elevation of GH and insulin-like-growth factor-1 (IGF-1) levels." (PMID 37210433, 2023). "The pituitary gland is an important endocrine organ, and the development of PA is accompanied by endocrine changes, and serum PRL, IGF-1, and GH determinations are the main basis for the diagnosis of pituitary tumors." (PMID 35356252, 2022). "The main endpoints were long-term safety (comorbidities, adverse events (AEs), pituitary tumour volumes, liver tests) and efficacy (IGF1 changes)." (PMID 34342594, 2021). "Overall, age >40 years, IGF-1 xULN at diagnosis and T2-hypointense pituitary tumor had an excellent discriminative ability to predict a >50% IGF-1 reduction after 6-month SRL treatment (AUC 0.98, 95%CI 0.93-1.0)." (PMID 34025586, 2021). "This slowly progressive disease is caused by a chronic excess of growth hormone (GH) and consequently by increased circulating insulin-like growth factor 1 (IGF-1), in most of the cases as a result of a sporadic GH-secreting pituitary tumor." (PMID 30034367, 2018). "Factors associated with increased mortality in the KIMS database were female gender, younger attained age, aggressive pituitary tumors, and lower insulin-like growth factor 1 (IGF-I) standard deviation score during therapy." (PMID 29225782, 2017). "The initial laboratory test revealed insulin-like growth factor 1 (IGF-1) level of 880ng/mL and a GH level of 8.70ng/mL, which are compatible with a GH-producing pituitary tumor." (PMID 25182385, 2014). "A short-term post-traumatic laboratory test showed high levels of insulin like growth factor 1 and growth hormone, which are compatible with a growth hormone–producing pituitary tumor." (PMID 25182385, 2014). "The discrepancy between GH and IGF-1 in predicting dural invasion allows us to hypothesize that GH may exert autocrine- or paracrine-stimulating effects on the pituitary tumor itself." (PMID 39685770, 2024). "Furthermore, GH-secreting pituitary tumors with variants in BCHE, DARS, NGDN, and UNC5B presented high biochemical activities including GH and IGF-1." (PMID 34400688, 2021).
pituitary tumor (continued). "Based on previous data from the literature, the link between IGF-1 levels at diagnosis and the MRI features of the pituitary tumor could, at least partially, explain our findings." (PMID 34025586, 2021). "IGF-1 normalization according to pituitary tumor characteristics." (PMID 24039977, 2013). "Our patient had CM1, a nonfunctioning pituitary tumor, and normal GH and IGF-1 levels, raising the possibility of another underlying mechanism, perhaps a genetic predisposition, contributing to the concomitant occurrence of CM1 with pituitary and adrenal tumors and an adrenal myelolipoma." (PMID 38919912, 2024). "The 2 patients who exhibited the most significant declines in IGF-1 levels following clomiphene therapy had clinically nonfunctioning pituitary tumors, which are often large pituitary lesions at presentation." (PMID 40421427, 2025). "Only one patient had a history of transsphenoidal pituitary tumor resection before admission, and the relevant patient was admitted into our hospital this time because of tumor recurrence and nonremission of GH and IGF-1." (PMID 32148485, 2020). "This represents a significant association of pathology diagnosis with abnormal glucose metabolism at the time of diagnosis that was independent of pituitary tumor size, invasiveness, or presenting GH or IGF-1 levels." (PMID 24039977, 2013). "Experimental studies showing the permissive role of GH/insulin-like growth factor 1 (IGF-I) in carcinogenesis have raised concerns regarding the safety of GH replacement in children and adults who have received treatment for cancer and those with intracranial and pituitary tumours." (PMID 35319491, 2022). "Besides the proband (IV:4), nonfunctioning pituitary tumors were identified in three carriers of the CDKN1B variant, including two microadenomas (III:4 and III:7) and one macroadenoma (IV:1), with functionality classified on the basis of measurements of IGF-1 and prolactin." (PMID 30990521, 2019).
endometriosis (56 papers, 2013 to 2025). The growth of functional endometrial tissue in anatomic sites outside the uterine body. "They identified that disease-modified macrophages exhibit increased expression of IGF-1 in an in vitro model of endometriosis-associated macrophages, and confirmed expression by lesion-resident macrophages in mice and women." (PMID 37242543, 2023). "IGF1 expression is elevated in patients with endometriosis and IGF1 signaling is associated with endometrial regeneration." (PMID 37626707, 2023). "IGF-1 is regulated by endometriosis-associated macrophages and it promotes sprouting neurogenesis and nerve sensitization in vitro." (PMID 33435569, 2021). "Taken together, macrophages are evidently pivotal to facilitating neurogenesis and the generation endometriosis-associated pain symptoms, and this is at least in part mediated by IGF-1." (PMID 32038499, 2020). "To further explore the role of Igf-1 in mice with endometriosis-associated pain, we inhibited Igf-1r using linsitinib, a selective IGF-1R inhibitor that prevents autophosphorylation and activation of downstream signaling." (PMID 31291762, 2019). "Although these limited studies have inferred a role for IGF-1 in the pathophysiology of endometriosis, the current study is the first to implicate a role for IGF-1 in endometriosis-associated pain." (PMID 31291762, 2019). "We aimed to further explore the importance of IGF-1 in the mechanism behind endometriosis-associated pain in women using human samples of PF." (PMID 31291762, 2019). "We identified that disease-modified macrophages exhibit increased expression of IGF-1 in an in vitro model of endometriosis-associated macrophages and confirmed expression by lesion-resident macrophages in mice and women." (PMID 31291762, 2019). "To determine potential mechanistic roles for macrophage-derived IGF-1 in endometriosis-associated pain, we explored the effects of EAM-conditioned medium on neuronal cell cultures." (PMID 31291762, 2019). "Our results are in line with a prior study in the NHSII population showing that blood IGF1 levels were positively associated with endometriosis risk among younger women (age<40 years at blood draw), and adds further insight into the additional proteins that contribute to the IGF transport pathway." (PMID 40215752, 2025). "Endothelin and IGF-1 may also play a role in endometriosis-associated angiogenesis as their levels were found to be significantly higher in women with endometriosis compared to controls." (PMID 35449709, 2022). "Finally, we were able to infer a strong link between macrophage-derived IGF-1 and the observed endometriosis-associated changes in sensory behavior using mechanistic in vitro models." (PMID 31291762, 2019). "Our study suggests that macrophages or signaling resulting from factors that they produce such as IGF-1 could be targeted to alleviate endometriosis-associated pain in women." (PMID 31291762, 2019). "Macrophage-derived IGF-1 may play a role in endometriosis-associated pain." (PMID 37242543, 2023). "HGF and IGF-1 have several physiological and pathological effects that could contribute to the survival, proliferation, and invasion of endometrial stromal cells (ESCs) associated with endometriosis." (PMID 34930225, 2021). "In endometriosis, all IGF1 isoforms are expressed in eutopic endometrium and ovarian endometrioma, but their levels significantly decrease in endometriotic cysts." (PMID 39796756, 2025). "Our results showing IGF1 increasing and IGFBP1 and IGFBP4 reducing the odds for an endometriosis diagnosis suggest an opposing function of IGF1 and their binding proteins in bloods collected years prior to endometriosis diagnosis." (PMID 40215752, 2025). "The results presented in this study concerning the analysis of VEGF, IGF1/2 and H19 genes show the presence of certain dependencies of their expression with endometriosis." (PMID 38791310, 2024).
endometriosis (continued). "A significant reduction in IGF1 expression in cystic endometriosis was observed compared to eutopic endometriosis in women with endometriosis." (PMID 38791310, 2024). "The aim of the study was to analyze the expression levels of the VEGF, IGF1/2 and H19 genes in patients with endometriosis and in the control group." (PMID 38791310, 2024). "In our study, we have shownthat the expression of both H19 and IGF1 is significantly reduced in women with endometriosis." (PMID 38791310, 2024). "IGF1 levels were reduced in the eutopic endometrium in endometriosis compared to control endometrial samples, while increased IGF1 expression was observed in fibrotic peritoneal adhesions." (PMID 38791310, 2024). "IGF1 has been reported as a hub gene in the bioinformatic analysis of endometriosis transcriptomics data." (PMID 37626707, 2023). "The current study aims to shed light on the expression as well as potential role of IGF-1 isoforms in endometriosis, a field that has been poorly investigated thus far." (PMID 38275748, 2023). "The expression of all isoforms of IGF-1 was significantly higher in the endometriosis group than in the control group (p-value IGF-1Ea: 0.001, p-value IGF-1Eb < 0.001, p-value IGF-1Ec: 0.000 < 1)." (PMID 38275748, 2023). "Several studies have shown increased activity of IgF-1 in the peritoneal fluid of women with endometriosis." (PMID 38275748, 2023). "IGF-1, found in peritoneal fluid, is thought to contribute to endometriosis by stimulating the growth and preventing apoptosis of endometrial-like cells." (PMID 37242543, 2023). "Specifically, in the eutopic endometria of women with endometriosis, a reduction in staining was observed, whereas in the epithelial cells of fibrotic peritoneal adhesions, intense immunostaining for IGF-1 was observed." (PMID 38275748, 2023). "By reviewing the existing literature regarding the possible role of IGF-1 on the pathogenesis and pathophysiology of endometriosis, it is evident that this important growth factor remains largely understudied." (PMID 38275748, 2023). "Concentrations of IGF-1 were elevated in peritoneal fluid from women with endometriosis and positively correlated with their pain scores." (PMID 37242543, 2023). "Gene expression of IGF‐1 in PFMCs of endometriosis patients showed a significant decrease after 24 and 48 h following 1,25(OH)2D3 treatment (p < 0.05 and <0.01, respectively)." (PMID 36259314, 2022). "1,25(OH)2D3 treatment reduced the gene expression of IGF‐1 in PBMCs of endometriosis patients and non‐endometriotic individuals at 24 h (p < 0.05)." (PMID 36259314, 2022). "Protein expression of IGF‐1 also decreased significantly in PFMCs of endometriosis patients after 24 and 48 h following 1,25(OH)2D3 treatment (p < 0.05)." (PMID 36259314, 2022). "Since endometrioma indicates late stages of endometriosis, reduction of IGF1 expression in cysts is likely related to the disease status." (PMID 35459174, 2022). "Our results showed that women with endometriosis had decreased IGF1 expression as well as decrease in the level of IGF2 expression in the eutopic and ectopic endometrium of endometriosis group compared to the controls." (PMID 35459174, 2022). "Studies on the association between IGF‐1 and endometriosis were inconsistent, but according to a recent prospective study, IGF‐1 and IGFBP‐3 were associated with a higher risk of endometriosis among younger women." (PMID 36259314, 2022). "The levels of MCP-1, HGF, and IGF-1 in serum and PF in women with endometriosis were significantly higher than the controls (P < 0.05–P < 0.001)." (PMID 34930225, 2021). "It is demonstrated that a substantial amount of IGF-1 was also produced by PFMCs at the level of mRNA and protein in women with endometriosis (P < 0.05 and P < 0.01, respectively) (Figs. 3Ba and Bb)." (PMID 34930225, 2021).